CXCL10 (C-X-C motif chemokine ligand 10)
Diseases named in the same sentence as CXCL10 in open-access papers (continued):
Sharing a sentence is not in itself a finding about the gene and the disease.
anthrax (1 paper, 2010). "Combinatorial neutralization of CXCL9 together with CXCL10 or CXCL10/CXCL11 during pulmonary B. anthracis infection significantly increased host susceptibility to anthrax, with neutralization of all three CXC chemokines resulting in 50% mortality (p = 0.0003)." (PMID 21124994, 2010). "To gain insight into disease progression associated with the neutralization of CXCL9, CXCL10, and CXCL11, and to confirm that host death resulted as a consequence of B. anthracis infection, we investigated two salient features of anthrax: bacterial dissemination and toxemia." (PMID 21124994, 2010). "As the induction of the interferon-inducible ELR- CXC chemokines within the lungs of spore-challenged mice is associated with resistance to inhalational anthrax, we sought to determine whether murine CXCL9, CXCL10, and CXCL11 exert antimicrobial activity against B. anthracis Sterne strain." (PMID 21124994, 2010).
apical periodontitis (1 paper, 2025). "Notably, the upregulation of CXCL10 has been observed in human samples during the progression of apical periodontitis." (PMID 41099523, 2025).
autoimmune pancreatitis (1 paper, 2024). "A positive feedback loop consisting of IFN-alpha CXCL9, CXCL10, and CCL25 mediates experimental and human autoimmune pancreatitis." (PMID 39264798, 2024).
autoimmune uveitis (1 paper, 2024). An autoimmune form of uveitis (disease). "Cxcl10 was also found to be significantly upregulated by Müller glia by differential expression between EAU and healthy retinas, thus indicating an acquired interaction that only occurs during autoimmune uveitis." (PMID 39198470, 2024).
Becker muscular dystrophy (1 paper, 2021). Becker muscular dystrophy (BMD) is a neuromuscular disease characterized by progressive muscle wasting and weakness due to degeneration of skeletal, smooth and cardiac muscle. "In this study, we used a highly specific and reproducible MSD ELISA assay to examine the levels of the three chemokines (CXCL10, CCL2, and CCL18) in serum and muscle samples collected from DMD patients, Becker muscular dystrophy (BMD) patients, and age-matched healthy controls." (PMID 34440571, 2021).
benign prostatic hyperplasia (1 paper, 2021). A non-cancerous nodular enlargement of the prostate gland. "Increased cytokines in benign prostatic hyperplasia (BPH) could induce BPH cells to produce inflammatory mediator, including IL-6, IL-8, and CXCL10 to create a positive feedback loop that can amplify inflammation." (PMID 34659199, 2021).
BK-virus nephropathy (1 paper, 2022). "CXCL9 has previously been shown to have diagnostic potential as urine biomarker within TCMR and BK virus nephropathy together with CXCL10." (PMID 35204399, 2022).
bladder disorders (1 paper, 2017). "Chemokines are known contributors to symptoms of bladder disorders, and Perters found remarkably reduced levels of chemokines CXCL-1, CXCL-10, and CCL-2 in patients who had received sacral neuromodulation therapy for BPS/IC." (PMID 28106785, 2017).
bone cancer (1 paper, 2025). A primary or metastatic malignant neoplasm affecting the bone or articular cartilage. "The mechanism by which fractalkine (CX3CL1) and CXCL10 are involved in bone cancer pain development through the activation of spinal microglia involves multiple steps and signaling pathways." (PMID 41416066, 2025).
bone marrow failure (1 paper, 2023). "G-CSF, Flt3L, and CXCL10 (IP-10) were increased in the sera from DC patients who developed severe bone marrow failure, whereas RANTES was lower than in DC patients with mild to moderate bone marrow failure or healthy subjects." (PMID 37627314, 2023).
borderline leprosy (1 paper, 2024). A form of leprosy in which there are clinical manifestations of both principal types (lepromatous and tuberculoid). "More severe types of the disease are frequently linked to higher levels of CXCL10, which has been discovered to be helpful in identifying T1R reactions in cases of borderline leprosy, as T1R reaction have been found to have higher levels of CXCL10." (PMID 38590701, 2024). "There was significant difference CXCL10 expression between borderline leprosy (BB) and BB-T1R, where BB-T1R have higher expression than BB." (PMID 38590701, 2024). "Differences in CXCL10 levels was seen between borderline leprosy (BB) and BB-T1R (p < 0.05)." (PMID 38590701, 2024). "It was shown that mRNA expression levels of CXCL10 from skin biopsies of borderline leprosy cases with or without T1R was consistently high." (PMID 38590701, 2024).
Brain atrophy (1 paper, 2021). Partial or complete wasting (loss) of brain tissue that was once present. "The CHI3L1 (chitinase-3-like protein 1) level in the CSF was strongly correlated with brain atrophy, and the CSF levels of CXCL1, MMP-9, CCL22, CXCL13, and CXCL10 were correlated with the development of new lesions in T2 MRI." (PMID 34602928, 2021).
C. perfringens infection (1 paper, 2024). "Meanwhile, the expression levels of CXCL10 and IFN-β were significantly increased in HKCA training PM compared with the control cells after C. perfringens infection." (PMID 38622656, 2024).
Candidemia (1 paper, 2025). A form of invasive candidiasis where species of CANDIDA are present in the blood. "The proteomic profile in candidemia included eight of the most significantly upregulated DEPs: CXCL11, LAP-TGF beta-1, CD40, CXCL1, CXCL6, IL18, CXCL10, and uPA." (PMID 41229429, 2025). "The highest upregulated expressions in isolated candidemia included CXCL6, LAP-TGF beta-1, CXCL1, CXCL11, and CD5, while in candidemia with bacterial co-infection, CXCL11, CD40, uPA, CXCL1, CXCL10, and IL-18 were the most abundantly upregulated." (PMID 41229429, 2025).
cervical tumors (1 paper, 2015). "This approach is novel as it hypothesizes CXCL10 may enhance the radiosensitivity of cervical tumors in nude mice." (PMID 26622567, 2015). "Overall, the present study indicated that the combination of CXCL10 gene therapy and radiotherapy is an efficient strategy for growth suppression in cervical tumors, which may result from the attenuation of angiogenesis, decline in cell proliferation and induction of apoptosis." (PMID 26622567, 2015).
choroidal neovascularization (1 paper, 2024). An eye disorder described by the growth of new blood vessels that originate from the choroid through a break in the Bruch membrane into the sub–retinal pigment epithelium (sub-RPE) or subretinal space. "We previously established CXCL10 as an antiangiogenic agent both in vitro and in vivo in different mouse models of vasoproliferative eye diseases as the VLDR or laser choroidal neovascularization (CNV) model." (PMID 38190125, 2024).
chronic allograft nephropathy (1 paper, 2024). "The serum levels of CXCL10, which is widely expressed in chronic allograft nephropathy tissues, help predict graft loss." (PMID 39715172, 2024).
chronic lung allograft dysfunction (1 paper, 2019). Chronic lung allograft dysfunction encompasses a range of pathologies that cause a transplanted lung to not achieve or maintain normal function. "We previously showed that CXCL10 and cfDNA, as measured via the KIT assay, can detect chronic lung allograft dysfunction in lung transplantation as well as rejection in kidney transplantation." (PMID 31013714, 2019).
colorectal adenoma (1 paper, 2014). An adenoma that arises from the colon or rectum. "Furthermore, few studies simultaneously evaluated several serum adipokines, and we could find no other studies evaluating the relationship between serum IP-10/CXCL10 and colorectal adenoma." (PMID 24465801, 2014).
congenital toxoplasmosis (1 paper, 2020). Toxoplasma infection that is present from birth. "We propose the levels of CXCL9 and CXCL10, the frequencies of CD4+CD25+ T-cells and the frequency of T. gondii-specific IFN-γ producing CD4+ T-cells presented as biomarkers able to distinguish with high accuracy infants with congenital toxoplasmosis from uninfected healthy controls." (PMID 33028847, 2020).
Cough (1 paper, 2017). A sudden, audible expulsion of air from the lungs through a partially closed glottis, preceded by inhalation. "Poly(I:C), as expected, up-regulated genes associated with inflammation, innate immunity and viral responses including CXCL11, CCL5 (chemokine (C–C motif) ligand) 5 and CXCL10, interferon-induced protein 44 like (IFI44L) in ASMCs from both healthy non-cough and chronic cough volunteers." (PMID 28842514, 2017).
crescentic glomerulonephritis (1 paper, 2023). A histopathologic term for a pattern of diseases characterized by extensive crescent formation in the glomeruli; patients present clinically with rapid deterioration of renal function, and possible progression to end-stage renal failure within weeks or months. "GC has been shown to inhibit the induction of CXCL10 in tubular epithelial cells to prevent renal infiltration of CXCR3+CD4+ T cells and subsequent renal tissue damage in patents and mice with crescentic glomerulonephritis." (PMID 39619227, 2023).
Cryptococcal meningitis (1 paper, 2025). Meningeal inflammation produced by cryptococcus neoformans, an encapsulated yeast that tends to infect individuals with acquired immunodeficiency syndrome and other immunocompromised states. "Our study suggests that mortality following cryptococcal meningitis is associated with paucity of CSF CXCR3+ T cell activating chemokine CXCL10, cellular growth activating cytokine IL-2, and immune checkpoint regulatory element PD-L1." (PMID 39928682, 2025). "With survival, after adjusting for cytokine and chemokine responses, IL-2 (p = 0.0353) and CXCL10 (p = 0.0045) independently predicted survival with cryptococcal meningitis (model 1 and S7)." (PMID 39928682, 2025). "18-week survival after diagnosis of cryptococcal meningitis was associated with higher CSF leukocytes at baseline with greater T helper 1 (IFN-γ, IL-2 and TNF-α cytokines), T helper 17 (IL-17A cytokine) and CXCR3+ T cell (CXCL10 chemokine) responses." (PMID 39928682, 2025). "Other variables including peripheral white blood cells, PD-L1, CXCL10, CCL11, IFN-γ, IL-2 and IL-10 did not independently predict the levels of CSF leukocytes count with cryptococcal meningitis." (PMID 39928682, 2025).
cutaneous sarcoidosis (1 paper, 2023). "The implication of IFN-γ on Mɸ in human skin is underlined by its effects on Mɸ immunologic reprofiling: in cutaneous sarcoidosis, IFN-γ-related expression of downstream translational targets includes STAT1, CEBPB, FN1, TREM1, CXCL9, CXCL10, IL-6, and others." (PMID 36902053, 2023). "The role of IFN-γ in cutaneous sarcoidosis is reinforced by the observation that IFN-γ-inducible chemokines CXCL9 and CXCL10 are elevated in serum and tissue of patients with systemic sarcoidosis, and blood transcriptional profiles show IFN-γ-related signaling pathways in such patients." (PMID 36902053, 2023).
cutaneous T-cell lymphoma (1 paper, 2023). "Work from our collaborators demonstrated that GaM decreased the expression of pro-angiogenic cytokine IL-10 in a mouse model of cutaneous T-cell lymphoma, whereas angiostatic proteins CXCL10 and CXCL11 were significantly upregulated." (PMID 38288102, 2023).
diabetic eye disease (1 paper, 2024). A group of disorders affecting the eye in patients with diabetes mellitus. "Network meta-analysis revealed that CCL8, CCL2, CXCL8 and CXCL10 may be involved in key pathophysiological process of diabetic eye disease." (PMID 38790059, 2024). "Specifically, this network meta-analysis indicated that CC chemokines (CCL8 and CCL2) and CXC chemokines (CXCL8 and CXCL10) may discriminate between those with and without diabetic eye disease." (PMID 38790059, 2024).
dilated cardiomyopathy (1 paper, 2022). Cardiomyopathy which is characterized by dilation and contractile dysfunction of the left and right ventricles. "While CXCL9, CXCL10, and CXCL11 belong to the chemokine family, CX3CR1, ADORA3 and SAA1 have not been reported in dilated cardiomyopathy, and further research is needed." (PMID 35618744, 2022).
ductal adenocarcinoma (1 paper, 2024). "Indeed, plasma levels of IFN-ɣ-inducible chemokines CXCL9 and CXCL10 have been correlated with survival and chemotherapeutic efficacy in advanced ductal adenocarcinoma." (PMID 38167224, 2024).
duodenal ulcer (1 paper, 2013). An ulcer in the duodenal wall. "The results of the present study showed the lower serum concentrations of CXCL10 in H. pyloriinfected PU patients (including patients with gastric or duodenal ulcers) in comparison to AS and control groups." (PMID 23467184, 2013).
dystrophin deficiency (1 paper, 2021). "To verify if the increased levels of these three chemokines are effectively associated with dystrophin deficiency, we conducted ELISA assays to measure CCL2 and CXCL10 on serum samples collected from mdx-23 mice (n = 10) and wild-type mice (n = 14)." (PMID 34440571, 2021). "Interestingly, CCL2, but not CXCL10, was significantly elevated in serum samples of the mdx mouse model for DMD relative to wild-type mice, further suggesting that increased levels of this circulating CCL2 may be associated with muscle pathogenesis due to dystrophin deficiency." (PMID 34440571, 2021).
echinococcosis (1 paper, 2022). A parasitic infection caused by tapeworm larvae of Echinococcus. "Higher serum CXCL10 levels may recruit more CD4+ T cells for metastasis to the liver, leading to a more severe immune response; echinococcosis might have a similar mechanism." (PMID 36034715, 2022).
enteropathy (1 paper, 2014). "Because Th1 cells characteristically express CXCR3 and certainly take part in the damage mechanisms that cause severe enteropathy, the aim of this work was to assess the role of the CXCL10/CXCR3 axis in lymphocytic recruitment in active CD." (PMID 24586509, 2014). "Consequently, CXCL10 showed a strong correlation with IFNγ expression in the intestinal mucosa in normal tissues and in severe enteropathy." (PMID 24586509, 2014).
esophagitis (1 paper, 2026). An acute or chronic inflammatory disease affecting the esophageal wall. "In contrast, EoE-like esophagitis was primarily immune-driven, marked by CXCR3 ligand activation (CXCL9, CXCL10, CXCL11) and immunoglobulin complex enrichment, indicating systemic immune dysregulation and a potential precursor state to conventional EoE." (PMID 41818315, 2026).
fibromyalgia (1 paper, 2022). A chronic disorder of unknown etiology characterized by pain, stiffness, and tenderness in the muscles of neck, shoulders, back, hips, arms, and legs. "The top five proteins that distinguished fibromyalgia patients from plasma controls were in serum STAMBP, SIRT2, CD40, AXIN1 and IL-7 and in CSF (CCL19, CCL23, IL-18, CX3CL1, FGF19, CXCL10, CCL11)." (PMID 36327322, 2022).
gallbladder cancer (1 paper, 2022). "In the study of gallbladder cancer with ErbB pathway mutation, the interaction between CXCL10 and CXCR3 secreted by macrophages is induced, thus promoting the progression of gallbladder cancer." (PMID 36479091, 2022). "They found that immuno-suppressive macrophages increased expression of CXCL10 that binds to its receptor CXCR3 on Treg cells, eliciting tumor immune resistance in ErbB-mutation gallbladder cancer." (PMID 36479091, 2022).
gastroduodenitis (1 paper, 2016). "For example, in H. pylori positive gastroduodenitis we demonstrate increased serum levels of chemoattractants for mononuclear lymphocytes, such as CXCL10, CCL22, and CXCL16." (PMID 28018296, 2016).
gastroparesis (1 paper, 2019). Paralysis of the muscles of the stomach wall resulting in delayed emptying of the gastric contents into the small intestine. "Several of the predicted PI3K target genes were further examined by qRT-PCR, of these CXCL10 was found to be specifically elevated in high BMI control subjects, whereas HMOX1 and SREBF1 were decreased both in high BMI control subjects and in low BMI subjects with idiopathic gastroparesis." (PMID 31221130, 2019).
Gaucher disease (1 paper, 2022). Gaucher disease (GD) is a lysosomal storage disorder encompassing three main forms (types 1, 2 and 3), a fetal form and a variant with cardiac involvement (Gaucher disease - ophthalmoplegia - cardiovascular calcification or Gaucher-like disease). "The data presented a unique nGD-associated pattern favoring pro-inflammatory mediators with Cxcl10 elevating the most in an adult genetic model of neuronopathic Gaucher disease." (PMID 36204141, 2022).
hearing loss (1 paper, 2024). "The expression of CXCL10 is increased in acute noise induced hearing loss, which promotes immune-mediated apoptosis in the ear and induces age-related deafness in humans." (PMID 39764513, 2024).
hemoglobinopathies (1 paper, 2020). "Thus, our results suggest that chemokines CXCL10 and CCL2 and cytokines, TNF-α, IL-8, and IL-6 may contribute to the overall pro-inflammatory response and could be utilized for predicting the severity of Plasmodium infection or a hemoglobinopathy." (PMID 33424841, 2020).
hemorrhagic fever with renal syndrome (1 paper, 2020). A viral infectious disease that is a hemorrhagic fever, located_in kidney, has_material_basis_in Hantaan virus, has_material_basis_in Dobrava-Belgrade virus, has_material_basis_in Seoul virus, or has_material_basis_in Puumala virus, which are carried and transmitted_by rodents. "Notably, another study underscored that Hantaan virus, the pathogen of hemorrhagic fever with renal syndrome (HFRS), promotes the secretion of CXCL10 by facilitating NF-κB and IRF7 to directly bind to the promotor of CXCL10 in the downstream of MDA569." (PMID 32532953, 2020).
herpes simplex infection (1 paper, 2024). "We also found a certain positive relationship between OAS2, CXCL10, and herpes simplex infection." (PMID 39091676, 2024).
histiocytic lymphoma (1 paper, 2017). "IP-10 (CXCL10) was initially known as an early, transiently expressed, interferon (IFN) γ-inducible gene in a histiocytic lymphoma cell line with monocytic characteristics." (PMID 28346545, 2017).
histiocytic sarcoma (1 paper, 2025). An aggressive malignant neoplasm with a poor response to therapy, usually presenting as stage III/IV disease. "In the present study, an increase in the expression of CXCL10 under both hypoxia and starvation indicates its potential role in promoting tumor development in canine histiocytic sarcoma." (PMID 40724877, 2025).
HIV-associated neurocognitive disorder (1 paper, 2025). HIV-associated neurocognitive disorder (HAND) remains a common complication of HIV infection in the combination antiretroviral therapy (ART) era. "Some studies have reported gender-related differences in the concentrations of CXCL-12 and CXCL-10 in serum and plasma samples from patients with inflammatory responses due to spinal cord injury and HIV-associated neurocognitive disorder (HAND)." (PMID 39861878, 2025).
hydronephrosis (1 paper, 2014). Collection of urine in the renal pelvis that results in dilatation of the renal pelvis and calyces. "In this regard, chemokines like CCL2/MCP-1, CCL5/RANTES, macrophage inflammatory protein-2 (CXCL2/MIP-2), and γ-interferon-inducible protein (CXCL10/IP-10) have been evaluated in experimental hydronephrosis." (PMID 24692841, 2014).
hypertriglyceridemia (1 paper, 2023). A laboratory test result indicating elevated triglyceride concentration in the blood. "In that period, triglyceride levels negatively correlated with CXCL10 and CXCL11, both chemokines known to cause hypertriglyceridemia." (PMID 36692327, 2023).
Hypofibrinogenemia (1 paper, 2020). Decreased concentration of fibrinogen in the blood. "The correlation network analyses between the molecules evaluated in the present study show that, in the group of patients with hypofibrinogenemia, it was possible to observe a predominance of a chemoattractive profile, with correlations between chemokines CXCL-8, CXCL-9, CCL-2, and CXCL-10." (PMID 32973773, 2020).